EPCAM (epithelial cell adhesion molecule)
Diseases named in the same sentence as EPCAM in open-access papers (continued):
Sharing a sentence is not in itself a finding about the gene and the disease.
cancer (continued). "EpApt-siEp appears to eliminate EpCAM-positive cancer cells while leaving healthy EpCAM-negative cells." (PMID 34439139, 2021). "With the expression of anti-EpCAM CAR, these CAR-expressing iNK cells displayed significantly higher cytotoxicity towards NK resistant, EpCAM-positive cancer cell lines BT474 and HTB131 in comparison with primary NK and unmodified iNK cells." (PMID 34802459, 2021). "EpCAM overexpression correlates with poor survival in some cancer types and better survival in others." (PMID 35008827, 2021). "Tregs display a higher degree of activation in the ascites than in blood, and the number of Tregs correlates with the proportion of epithelial cell adhesion molecule (EpCAM)+ cancer-derived epithelial cells in ascites fluid." (PMID 34503128, 2021). "As a result, single-cell transcriptome analysis revealed a clear difference in the expression level of a cancer biomarker gene (i.e., EpCAM) between different types of cancer cells (Kato III and MDA-MB-231 cells) at the single-cell level." (PMID 35479393, 2021). "As the cancer cell-derived exosomes are generated by inward cell budding, they also possess the EpCAM on their surface (such exosomes can be used as an indicator of cancer stages)." (PMID 33494499, 2021). "As most cancers are of epithelial origin, the most common marker used for CTCs is EpCAM, a “universal” epithelial marker of cancers." (PMID 34803167, 2021). "A widely known CTC biomarker is the epithelial cell adhesion molecule (EpCAM), a pan-cancer biomarker which has also been observed in HCC patients." (PMID 34503144, 2021). "Currently, one CAR-EpCAM T-cell clinical trial (NCT03013712) has been registered and is recruiting EpCAM-positive cancer (including HCC)." (PMID 33537099, 2021). "Spatiotemporal cell-specific expression of EpCAM is best exemplified in differentiating ESCs and in malignant cells during cancer progression." (PMID 34693227, 2021). "There are specific types of exosomal proteins that act to discriminate between different cell types; for example, the epithelial cell adhesion molecule (EpCAM) differentiates between cancer cells and normal cells." (PMID 34940275, 2021). "Edrecolomab was the first EpCAM-directed monoclonal antibody MAB (monoclonal antibody) approved for human cancers more than 30 years ago." (PMID 33543415, 2021). "Simultaneous assessment of CD45 and CD56 together with (surface membrane and cytoplasmic) CD3 and CD19, as well as numyogenin, EpCAM, CD271, and GD2, provides fast and highly accurate diagnostic orientation in children suspicious of having cancer." (PMID 34638431, 2021). "In an extended panel of human cancer cell lines, EpCAM expression is inversely correlated with CTSL activity." (PMID 33980181, 2021). "It was recently found that the replication of HBV is positively correlated to the expression of cancer stemness markers (EpCAM, CD44, CD133, NANOG, OCT4, and Sox2), tumorigenesis, and self-renewal." (PMID 33669204, 2021). "Catumaxomab is a bispecific artificial antibody binding to both epithelial cell adhesion molecule EpCAM, a cancer stem cell antigen, and CD3, resulting in the activation of immune cells." (PMID 34065315, 2021). "EpCAM expression can differentially regulate oncogenic signaling pathways and invasion depending on the cancer type." (PMID 33980181, 2021). "Of note, we are aware of variable EpCAM expression in “primary CTCs” versus established cancer cell lines." (PMID 34829387, 2021). "Together, these results demonstrate that secreted EpCAM inhibits secreted CTSL activity, while cancer-associated EpCAM mutations that prevent cell surface expression also prevent the ability to inhibit CTSL activity." (PMID 33980181, 2021).
cancer (continued). "We constructed CAR T cells targeting EpCAM that successfully showed selective cytotoxicity in highly EpCAM-expressing cancer cell lines." (PMID 34790117, 2021). "In tumors, it was reported that the cancer cells express certain surface adhesion molecules such as N-cadherin, galectin-3 and epithelial cell adhesion molecule (EpCAM), which are responsible for multicellular aggregate formation." (PMID 34070233, 2021). "In tumors, multi-cancer-cellular aggregation are usually ascribed to surface adhesion molecules (eg., epithelial cell adhesion molecule (EpCAM) and galectin-3) expressed on the surface of cancer cell membranes with homologous adhesion domains." (PMID 34952587, 2021). "Epithelial cell-activating molecule (EpCAM) is an important cancer biomarker and therapeutic target given its elevated expression in epithelial cancers." (PMID 34575064, 2021). "In general, CSC marker-positive cells (CD133+, CD44+, CD166+, aldehyde dehydrogenase (ALDH+), and epithelial cell adhesion molecule (EpCAM+)) exhibit a 100-fold increased capacity to initiate cancer." (PMID 33673439, 2021). "Krull and co-workers also used a similar oligonucleotide-based system where a quantum dot was conjugated to a single-stranded DNA aptamer that specifically binds the cancer biomarker protein epithelial cell adhesion molecule (EpCAM), immobilized on paper." (PMID 33477883, 2021). "EpCAM, which is representative of the markers used in positive enrichment techniques, is epithelial-specific and is strongly expressed in most cancers." (PMID 34798902, 2021). "EpCAM-positive stem cells in OC have a high tumorigenic potential, which further supports the development of anti-EpCAM therapy for preventing cancer progression." (PMID 34439094, 2021). "The extracellular domain of EpCAM is secreted (and/or cleaved) and is detectable in cell culture media and the serum and ascites of cancer patients." (PMID 33980181, 2021). "CSV has better performances than EpCAM in most cancers in regarding CTC detection rates, except for CRC." (PMID 33717672, 2021). "Many studies have shown that EpCAM and EpICD expression promotes cancer cell migration and invasion, a phenotype typically associated with EMT." (PMID 34209658, 2021). "On the other hand, the silencing of RARβ enhanced the expression of BIRC5 in A549 CD166+EpCAM+ and A549 CD166-EpCAM-, suggesting that depletion of RARβ promotes the cancer cell growth via activation of the anti-apoptosis gene." (PMID 33995625, 2021). "This supported the suggestion that EpCAM CAR T cells had stronger killing ability against EpCAM-expressing cancer cells than control T cells." (PMID 34790117, 2021). "Epithelial cell adhesion molecule (EpCAM) is another transmembrane glycoprotein that is overexpressed in various cancers including breast." (PMID 34769447, 2021). "In a recent study, an aptamer targeting the Tf receptor (TfR) was fused to an aptamer binding to EpCAM (epithelial cell adhesion molecule)-expressing cancer cells." (PMID 34959661, 2021). "Nrf2 knockdown reduced the expression of cancer stemness markers EPCAM, CD44 and Nanog in sorafenib-resistant Huh7 cells." (PMID 34473785, 2021). "While normally EpCAM is a proadhesion molecule, studies have shown that, in cancer, EpCAM can actually loosen the cell–cell interaction, thereby conferring advantages for metastasis." (PMID 34752419, 2021). "Anti-EpCAM-IgG-STMBs showed a capture efficiency of 79% of cancer cell lines spiked into healthy blood, with a release efficiency of 70% upon addition of biotin, releasing CTCs with 85% viability." (PMID 33652649, 2021). "The percentage of CD8+ T cells increased and was significantly greater than CD4+ T cells after co-culturing with EpCAM-positive cancer SW480 cells for 48 h." (PMID 34790117, 2021).
cancer (continued). "Additional immunofluorescence analyses were performed on HT-29 and MCF-7 spheroids, combining staining for CD68, CD11b, vimentin, and epithelial cell adhesion molecule (EpCam) to discriminate macrophages, fibroblasts, and cancer cells." (PMID 34451433, 2021). "EpCAM is a transmembrane protein expressed by normal epithelial cells and cancers of epithelial origin." (PMID 35008827, 2021). "The cellular PpIX fluorescence of cancer cell lines was comparable for cells bound to the different microchannel coating, namely the biocompatible polyoxazoline-based layer and the anti-EpCAM functionalized surface." (PMID 33790357, 2021). "We applied the method to a second cancer entity originating from squamous cell tissue with an epithelial, EpCAM-positive phenotype as proof-of-principle." (PMID 34829387, 2021). "Analysis of EpCAM’s expression patterns in diverse cancer specimen types has provided important insights into EpCAM’s role in EMT." (PMID 34209658, 2021). "Spheroids were collected to evaluate the cancer stem cells (CSCs) markers, such as EPCAM, CD133, and CD24, in HMGB1/RICTOR manipulated cells using real-time PCR methods." (PMID 34916485, 2021). "In liver cancer, histone lysine demethylase 4D (JMJD2D) reduced histone methylation levels and increased EpCAM and cancer stem marker SOX9 expression." (PMID 34209658, 2021). "In general, tumors of mesenchymal origin have low EpCAM expression, while cancers of epithelial origin have high EpCAM expression." (PMID 34209658, 2021). "The CTCs in the peripheral blood from HRP and cancer patients were enriched and identified based on the positive sorting method by epithelial cell adhesion molecular (EpCAM) liposome magnetic bead (Ep-LMB) and Vimentin liposome magnetic bead (Vi-LMB)." (PMID 34168982, 2021). "We opted to develop a COMSOL model to guide us to design, build and test flow through immunomagnetic separation of cancer cells using commercially available flow channels, an external magnetic array and magnetic particles directed against the EpCAM antigen." (PMID 34199434, 2021). "The group identified single-cell expression of HER2, epithelial cell adhesion molecule (EpCAM), estrogen receptor, and several other cancer-relevant protein biomarkers that can signal improved therapeutic choices." (PMID 33802356, 2021). "The detection of CTCs is usually dependent on molecular markers, with the epithelial cell adhesion molecule being the most widely used, although molecular markers vary between different types of cancer." (PMID 34803167, 2021). "Nevertheless, the poor isolation of CTCs by EpCAM-based technologies can be rescued by using both epithelial and mesenchymal cancer markers, as well as by marker-independent detection methods." (PMID 34803167, 2021). "There was no significantly different cytotoxicity against HPDE6-C7 between EpCAM CAR T and mGFP CAR T, and EpCAM CAR T showed good selectivity in inhibiting HCT116 cancer cell growth compared with HPDE6-C7 in RTCA." (PMID 34790117, 2021). "ESA or epCAM: Epithelial specific antigen (ESA), also known as epithelial cell adhesion molecule (epCAM) is a surface marker typically expressed on epithelial cells and has been used to identify CSCs in many types of cancer." (PMID 34884848, 2021). "have suggested that there is a subpopulation of cells CD44+/EpCAM+ with a high correlation with ALDHhigh cell populations which were previously shown to be cancer stem cells in NSCLC patients." (PMID 33868998, 2021). "CTC detection rates with EpCAM antibody are quite in accordance with EpCAM expression profiles in different cancers." (PMID 33717672, 2021). "Accumulated studies on the promotion of EMT by different parts of the EpCAM protein in numerous cancers should also be considered." (PMID 33691694, 2021). "They coated magnetic nanoparticles (MNPs) with antibodies against the epithelial cell adhesion molecule (EpCAM) using a microfluidic platform for the isolation process of cancer cells." (PMID 34832761, 2021).
cancer (continued). "EpCAM is an adhesion molecule known to play essential roles in cancer stemness biology of mainly epithelial derived cancers." (PMID 34550965, 2021). "It has been proven that EpCAM expression can be acquired during the progression of tumors with a high expression in cancer stem cells." (PMID 34063272, 2021). "More recently, the trifunctional antibody Catumaxomab, which targets EpCAM on epithelial cells and mitigates a multipronged, anti-cancer immune response, has been used in the treatment of malignant ascites in epithelial cancers." (PMID 34209658, 2021). "This suggests that the silencing of RARβ enhances the cancer growth in A549 CD166+EpCAM+ and A549 CD166-EpCAM- cell populations by EDN1 overexpression of the EDN1 gene which play important role in cancer metastasis." (PMID 33995625, 2021). "The trifunctional mAb catumaxomab (anti-EpCAM x anti-CD3) is approved in the European Union for treatment of malignant ascites in patients with EpCAM-positive carcinomas." (PMID 34439094, 2021). "The cell-surface protein EpCAM is a carcinoma marker utilized in diagnostics and prognostics, and a promising therapeutic target." (PMID 34055495, 2021). "The expression of EpCAM has been further demonstrated in numerous human normal epithelial tissues and carcinomas." (PMID 33691694, 2021). "In 2009 it was approved for the intraperitoneal treatment of malignant ascites in adults with Epithelial cell adhesion molecule (EpCAM) positive carcinomas." (PMID 34577584, 2021). "EpCAM was later described to be strongly and frequently expressed in the majority of carcinomas, in pluripotent embryonic stem cells (ESCs), and hepatic progenitors." (PMID 34693227, 2021). "Similar to EGFR, epithelial cell adhesion molecule (EpCAM) is frequently overexpressed on carcinomas but also present in healthy tissues, hindering systemic targeting due to toxicities." (PMID 33863363, 2021). "Epithelial cell adhesion molecule (EpCAM) is overexpressed in many carcinoma types with stem cell features." (PMID 34571870, 2021). "In light of the growing importance of cellular changes related to EMT in HNSCC and other carcinoma types, we have performed a technical comparison of manual and optical scoring systems for the central epithelial marker EpCAM and the EMT‐TF Slug in HNSCC." (PMID 33340247, 2021). "Clinical adverse events were reported in a recent Phase I study evaluating an epithelial cell adhesion molecule (EpCAM)-targeted BiTE as a therapy for a variety of epithelial carcinomas." (PMID 34378534, 2021). "Overexpression of HER2 and EpCAM in a large number of carcinomas, including OC, make them attractive targets for dual targeting." (PMID 34439094, 2021). "During physiological and pathological differentiation in ESCs and in carcinoma cells, respectively, EpCAM exhibits dynamic changes in expression levels and membrane localization." (PMID 34693227, 2021). "In this setting, the epithelial cell adhesion molecule (EpCAM) has been explored as a target antigen being overexpressed in carcinomas." (PMID 33959279, 2021). "The cell suspension was labeled with anti-CD326 (EpCAM) antibody, detecting human carcinoma cells, and/or a reagent detecting mouse cells bound to magnetic beads." (PMID 34944908, 2021). "EpCAM—transmembrane glycoprotein expressed in most human carcinomas; identified as a marker for carcinoma; can be attributed to its high expression on rapidly proliferating tumors of epithelial origin." (PMID 34203877, 2021). "For example, epithelial cell adhesion molecule (EpCAM) is highly expressed on the surface of various epithelial carcinomas." (PMID 34436082, 2021). "Overexpression of the EpCAM (epithelial cell adhesion molecule) in malignancies makes it an attractive target for passive immunotherapy in a wide range of carcinomas." (PMID 33543415, 2021).
cancer (continued). "The improved survival parameters in mice treated with ED-lip, suggest that the EpCAM-targeted-DOX liposome is a promising drug-delivery carrier for the treatment of cancers and merits further investigation." (PMID 32383027, 2020). "Due to the epithelial‐to‐interstitial transition, the recent CTC analysis method based on epithelial cell adhesion molecule (EpCAM) has a limited ability to detect CTCs in patients with malignant tumors." (PMID 32856417, 2020). "Specifically, as it is overexpressed in most cancer types, the epithelial cell adhesion molecule (EpCAM) represents the target antigen in most assays." (PMID 33353220, 2020). "EpCAM is a cell-surface transmembrane glycoprotein that is expressed in healthy human epithelial tissues but also in epithelial cancers, cancer stem cells, and inflammatory diseases." (PMID 32764280, 2020). "The Fisher group has also generated an armed oncolytic adenovirus to express a BiTE molecule which binds to epithelial cell adhesion molecule (EpCAM), a surface protein overexpressed on targeted cancer cells (EnAd-SA-EpCAM)." (PMID 32455560, 2020). "The flow cytometry analysis of the HuH-7 parental cell line showed that the cancer stem cell population carrying the EpCAM and CD133 surface markers (EpCAM+/CD133+) constituted around 1%–10% of the parental population." (PMID 32408542, 2020). "Our study revealed that Benz reduced STAT3, NF-κB, β-catenin, and CD326/EpCAM, which are cancer cell survival factors, as well as CSC/CIC markers, concomitant with the inhibition of a number of pro-tumorigenic malignancy events." (PMID 32102440, 2020). "Considering all published evidence across various cancers so far, EpCAM appears to be a generic marker of radioresistance." (PMID 33490064, 2020). "We have recently described the generation of a bifunctional aptamer that binds both to TfR and a cell surface receptor, the epithelial cell adhesion molecule (EpCAM), on cancer cells." (PMID 32027209, 2020). "As most cancers are epithelial in origin, targeting EpCAM therefore became the most commonly used epithelial marker for the capture of CTCs in the blood circulation of carcinoma patients." (PMID 32212818, 2020). "Since then, many studies have further corroborated that EpCAM is indeed an immunogenic molecule that can be targeted by monoclonal antibodies especially in cancers." (PMID 32046162, 2020). "The performance of this 3D foam was investigated using EpCAM-positive cancer cell lines (MCF7, breast cancer cells), resulting in a cell-capture yield reaching up to 58% after an incubation time of 30 min." (PMID 32466536, 2020). "EpCAM is a marker for cancer stem cells (CSC), and EpCAM positive breast cells are associated with CSC-like phenotype with increased metastatic ability." (PMID 32098281, 2020). "Catumaxomab, the first approved bispecific antibody, targets epithelial cell adhesion molecule (EpCAM) in cancer cells, and CD3 in T cells showed promising therapeutic effects in the treatment of malignant ascites." (PMID 32533270, 2020). "The Epithelial Cell Adhesion Molecule or EpCAM is a well-known marker highly expressed in carcinomas and showing a strong correlation with poor cancer prognosis." (PMID 32961790, 2020). "Treatment of high-density cells with ZEB reduced expression of surface markers (such as CD133, CD44, EpCAM) and cancer stem cell properties as well as tumorigenesis, concomitant with upregulation of genes related to apoptosis and differentiation." (PMID 32466488, 2020). "Integration analysis of TCGA (cancer tissues) and GTEx (normal tissues) RNA-seq data showed that EpCAM is overexpressed in the majority of cancer types compared to paired normal tissues." (PMID 32046162, 2020). "A drawback of using CTCs as diagnostic biomarkers is their apparent lack of specificity, as its detection relies on the use of pan-cancer markers such as epithelial cell adhesion molecule (EpCAM) and creatine kinase (CK), among others." (PMID 32443747, 2020).